MYOG (myogenin)
Diseases named in the same sentence as MYOG in open-access papers (continued):
Sharing a sentence is not in itself a finding about the gene and the disease.
tumor (continued). "Several kinds of monoclonal antibody were used to evaluate tumor cells immunohistochemically and included anti-Vimentin, CD31, CD34, cytokeratin (CK AE1/AE3, 34 β-E 12, 5/6, and CAM 5.2), desmin, α-smooth muscle actin (α-SMA), myoglobin, myogenin, and Ki-67 (MIB-1) antibodies." (PMID 21329505, 2011). "INI-1 was retained in the tumor cells, and WT1, desmin, myogenin, BCOR, TLE-1, CD45CLA, and synaptophysin were all negative (not shown)." (PMID 41230381, 2026). "Immunohistochemical examination showed that tumor cells were strongly positive for vimentin, SMA, and P16 but negative for desmin, CK, P40, P63, CK5, HMB45, MyoD1, myogenin, S100, and SOX10." (PMID 39872225, 2025). "Immunohistochemically, vimentin, smooth muscle actin (SMA), and P16 were diffuse positive in tumor cells, whereas desmin, cytokeratin (CK), P40, P63, CK5, HMB45, MyoD1, myogenin, S100, and SOX10 were all negative." (PMID 39872225, 2025). "Immunohistochemically, vimentin, SMA, and P16 were diffuse positive in tumor cells, whereas desmin, CK, P40, P63, CK5, HMB45, MyoD1, myogenin, S100, and SOX10 were all negative." (PMID 39872225, 2025). "The tumor cells were negative expression of CgA, CD56, CK5/6, CK20, Myogenin, MyoD1, Desmin, CEA, S100, CK8/18, CDX2, CD20, CD5, CD3, CD79a, LCA and HMB45." (PMID 38877473, 2024). "However, IF staining of tumor sections revealed that the tumor cells did not express MyoD1 and myogenin, markers of RMS cells, suggesting that this inconsistency between clinical SHP2 GOF mutation in patients and mouse sarcomagenesis could be associated with the origin and species of MSCs." (PMID 38451719, 2024). "Immunohistochemically (IHC), tumor cells were positive for SMA, MDM2, and p16; the cells were negative for desmin, MyoD1, Myogenin, pan-cytokeratin, S100, SOX10, HMB45, Malen-A, CD34, CD31, CD99, and ALK." (PMID 37735390, 2023). "Immunohistochemically, the tumor cells were positive for desmin, MYOD1 and SMA, focally positive for myogenin, while negative for h-caldesmon, SOX10 and S100P." (PMID 35642345, 2023). "Normally, BSNS tumours show immunoreactivity for S100, SMA and sometimes desmin but demonstrate no reaction with CD34, STAT6, EMA and myogenin, which was also included in the report of all three cases presented." (PMID 38027532, 2023). "Postoperative IHC revealed that the tumor was positive for desmin, S100, and EMA and negative for MyoD1, myogenin, CKpan, CD34, SMA, SOX-10, HMB, and MelanA." (PMID 37233406, 2023). "The tumor cells expressed SATB2, Bcl-2, TLE1, SMARCB1, but not CK, EMA, CD34, SMA, Desmin, S-100, CD99, STAT6, MyoD1, Myogenin, and Ki-67 LI is about 10%." (PMID 37361584, 2023). "Mitotic activity was low, and the tumor showed diffuse expression of α-SMA, desmin, caldesmon, and calponin, without expression of myogenin, MyoD1, CD34, EMA or PS100." (PMID 36421692, 2022). "The tumor was positive for CD117, Vim, CD56 and NSE and showed focal expression of desmin but was negative for myogenin, S-100, SYN, INSM1, CD34, STAT6, INI-1, Brachyury, ERG, TLE1, AE1/AE3, WT-1, CD99 and SMA." (PMID 35488288, 2022). "Immunohistochemically, the tumor cells were positive for CD117, vimentin, CD56 and NSE and focally expressed desmin; the cells were negative for myogenin, S-100, SYN, INSM1, CD34, STAT6, INI-1, Brachyury, ERG, TLE1, AE1/AE3, WT-1, CD99 and SMA." (PMID 35488288, 2022). "IHC studies show the tumor cells to be positive for FLI-1 and negative for S100 protein, SOX10, desmin, myogenin, WT1, SMA, CD34 and pan-cytokeratin." (PMID 34745213, 2021). "Immunostaining for HepPar1, CD34, CD117 (C-kit), S100, HMB45, myogenin, ALK-1, and α-fetoprotein were found to be negative in the primary tumor cells." (PMID 34162402, 2021). "The tumor cells were robustly and diffusely positive for Trk, S100-protein, CD34, and nestin, but negative for CD56, SMA, desmin, myogenin, STAT6, EMA, CK, CD1a, CD21, CD35, CD43, WT-1(c-terminal), MelanA, HMB45, BRAF, and ALK." (PMID 32957984, 2020).
tumor (continued). "The tumor cells were positive for Trk and SMA, but negative for S100, CD34, ALK, CD10, desmin, myogenin, CD99, CD56, CK, EMA, and STAT6." (PMID 32957984, 2020). "Like the tumours in SCID/beige mice, these tumours also showed variable staining for VIMENTIN, DESMIN and SMA as well as an absence of staining for MYOD1 and MYOGENIN." (PMID 29731980, 2018). "On reverse transcriptase polymerase chain reaction (RT-PCR) analysis, tumor cells lacked Myo D1, PAX3/7-FKHR transcripts and showed myogenin transcripts." (PMID 26208724, 2015). "On reverse transcriptase polymerase chain reaction (RT-PCR) analysis, tumor cells lacked Myo D1 and PAX3/7-FKHR transcripts and showed myogenin transcripts." (PMID 26208724, 2015). "The tumor cells were positive for CD99 and neuron specific enolase, negative for cytokeratin, leukocyte common antigen and myogenin." (PMID 25404964, 2014). "Immunohistochemically the tumor cells strongly expressed Vimentin, MyoD1, SMA and CD99, being negative for the remaining antibodies tested, including Myogenin and Desmin." (PMID 20701800, 2010). "Other immunohistochemical markers that may be focally positive and heterogeneous in tumor cells include desmin, CD68, vimentin, glypican‐3, and CD10, whereas myogenin, S‐100 protein, CD117, and HepPar 1 should be negative." (PMID 39587653, 2024). "The tumor diffusely expressed NUTM1, was positive for WT1cter at weak to moderate intensity, and was focally positive for CD99, while it was negative for keratins, EMA, P40, MyoD1, myogenin, NKX2.2, BCOR, and pan-TRK." (PMID 38851744, 2024). "IMT is the tumor that most frequently overexpresses ALK protein, however, in addition to no expression of skeletal muscle markers Myo-D1, Myogenin and Myogenin, genetically, IMT usually shows ALK re-arrangement with many other molecular partners including TPM3, KIF5B, CARS, and THBS1." (PMID 36998041, 2023). "On immunohistochemistry, the tumour cells showed diffuse positivity for S100 protein, and CD68; focal positivity for Inhibin, and Bcl2; and were negative for SMA, Myogenin, HMB45, and GFAP." (PMID 34514564, 2022). "(Immunohistochemical stains showed that the tumor cells were positive for desmin and TFE3, while negative for pancytokeratin, CAM5.2, EMA, chromogranin, synaptophysin, NSE, CD45, SMA, HHF35, myogenin, CD117, DOG1, MUC4, S100, SOX10, HMB45, Melan-A, CD31, ERG, TLE1, STAT6, and Cathepsin-K)." (PMID 35001360, 2022). "In addition, the neoplasms display varied expressions of desmin, CD30, SMA, and cytokeratin, while EMA, S100, CD117, Myf4, myogenin, h-caldesmon, and HMB45 are consistently negative." (PMID 35954326, 2022). "Cross striations may be appreciated and these tumours are positive for SMA, Desmin, and Myogenin, and are negative for S100P on immunohistochemical stains." (PMID 34514564, 2022). "However, the tumor cells were negative for S-100 protein, SMA, desmin, myogenin, CD99, Fli-1, CD56, STAT6, CK and EMA." (PMID 32957984, 2020). "No expression of myogenin, a specific skeletal muscle marker, was observed in tumours, and desmin, a general muscle marker, was heterogeneously and exclusively expressed in RST/A8 H2 tumours." (PMID 33303824, 2020). "None of the tumours exhibited nuclear staining for the skeletal muscle markers MYOD1 and MYOGENIN." (PMID 29731980, 2018). "The tumor cells are negative for leukocyte common antigen, HMB-45, Melan-A, desmin, and myogenin." (PMID 28143624, 2017). "Tumour cells were negative for leukocyte common antigen (LCA), S-100, WT1, desmin, myogenin, neuron specific enolase (NSE), CD34, CK7, and TTF-1 excluding lymphoma, melanoma, Wilms' tumor, rhabdomyosarcoma, neuroblastoma, epithelioid sarcoma, and rhabdoid large cell carcinoma of lung, respectively." (PMID 25243090, 2014). "No reactivity could be obtained in any tumor for cytokeratins, HMB 45, myogenin, CD 31, CD 34, factor VIII, and synaptophysin." (PMID 18593459, 2008).
tumor (continued). "Thirteen additional patients were screened but excluded because no tumor sample was available for analysis (n = 6) or because the diagnosis of RMS has not been confirmed by histological review (with different morphologic appearance and/or desmin and myogenin negative—n = 7)." (PMID 32087612, 2020). "Indeed, while these tumours showed high levels of H-RAS expression in comparison to adjacent normal tissue and were immunoreactive for the common mesenchymal marker VIMENTIN, the tumour cells did not stain for lineage markers including CD31, vWF, DESMIN, SMA, MYOD1 or MYOGENIN (last column)." (PMID 29731980, 2018). "However, negative for myogenic markers including desmin and myogenin, can readily exclude the possibility of embryonic RMS, and absence of expression of S100 protein and SOX10 together with retained expression of H3K27me3 disagree with a malignant triton tumor." (PMID 35125107, 2022).
cancer (20 papers, 2007 to 2025). A tumor composed of atypical neoplastic, often pleomorphic cells that invade other tissues. "In this study, the expression of key muscle differentiation factors such as MyoD and MYOG was also inhibited by cancer patient sera." (PMID 40283883, 2025). "Given that ID3 is downstream of C/EBPβ and loss of ID3 expression increases myogenin expression and promotes myogenic differentiation, we asked if the knockdown of ID3 could rescue differentiation in an in vitro cancer cachexia model." (PMID 30413755, 2018). "Increased Pax7 and decreased myogenin levels have been reported also in the cachectic muscle of mice bearing the C26 carcinoma and in cancer patients, opening the possibility that cancer-driven inflammation induces muscle atrophy, dysregulating SC differentiation program." (PMID 26508819, 2015). "Finally, normal D and cancer 3 retained common markers of CAPs, including RGS5, MCAM, and CRIP1, pathways relating to contractility and cytoskeletal rearrangements, and activity of transcription factors associated with muscle contractility, including MYOG." (PMID 40215177, 2025). "Adding cancer patient serum to the muscle differentiation evaluation system significantly reduced the expression levels of TNNT, MyoD, MEF2C, and MYOG compared to the control." (PMID 40283883, 2025).
infection (11 papers, 2009 to 2025). The state of being infected such as from the introduction of a foreign agent such as serum, vaccine, antigenic substance or organism. "It was also showed that mice immunized with gamma-irradiated Trichinella spiralis larvae are protected against infection, which leads to reduced muscle damage, Myogenin and Bcl-2 expression." (PMID 36538023, 2023). "A MuSC clone that expressed both Pax7-GFP reporter and MyoG-mCherry reporter post-infection in a hydrogel microwell was readily visualized by fluorescent time lapse microscopy." (PMID 36639373, 2023). "The expression of Myogenic Regulatory Factors Myf5, MyoD, Mrf4 and myogenin was modulated by the infection." (PMID 31828046, 2019). "As with C2C12 cells, infection of satellite cells with Pax3DN RV or Pax7DN RV led to significant reductions (p<0.0001) in the number of cells expressing either MyoD or myogenin (quantified in q)." (PMID 19221588, 2009). "Myogenic markers such as MyoD and Myogenin were reduced a few days after the infection." (PMID 36538023, 2023). "Compared to sh-NC, sh-DGAT2 infection of BSCs significantly inhibited the mRNA expression of PAX7, MYOD1, MYOG, and MYR4 (p < 0.05)." (PMID 35883393, 2022). "To further characterize the role of EPHB1 during myogenic differentiation, we analyzed expression of MYOD and MYOG in C2C12 cells 48 and 72 h respectively after infection, and found an increased number of cells expressing these myogenic markers." (PMID 27446912, 2016). "Transient infection with MyoD in shSIRT3 myoblasts restored differentiation to levels found in normal C2C12 myoblasts, as shown by myotube formation, positive Troponin T immunostaining and increased Myogenin expression of the infected cells." (PMID 25489948, 2014). "Also upregulated are PAX7, MYOG, and MYF5, all classic markers of myogenic differentiation and regeneration, indicating either inappropriate activation of muscle-lineage genes or potential cellular stress responses induced by prolonged infection." (PMID 40863220, 2025). "Notably, M. Ulcerans or mycolactone administration induces inflammation and myonecrosis, but fails to activate MuSCs, as shown by the absence of upregulation of the MRFs Pax7, MyoD, and Myogenin post-infection." (PMID 36538023, 2023).
myopathy (3 papers, 2010 to 2023). A disease of the muscle in which the muscle fibers do not function properly. "This, coupled with the absence of a regeneration response driven by an increase in PAX7, MYOD1 and myogenin, apparently cause the slow, progressive myopathy observed in Sil1Gt mice." (PMID 29666155, 2018). "Our mechanistical data on the role of SPSB1 in myogenic differentiation suggest the TβRII‐Akt‐Myogenin pathway contributes to defective muscle regeneration and myopathy observed in ICUAW patients." (PMID 37209006, 2023).
skeletal muscle disorder (1 paper, 2022). A disease involving the skeletal muscle tissue. "Some studies have shown that myogenin deficiency causes severe skeletal muscle disorders." (PMID 35741909, 2022).
MYOG also shares sentences with these, for which no sentence is quoted: Ewing sarcoma (5 papers); primitive neuroectodermal tumor (3); soft tissue sarcoma (3); synovial sarcoma (3); age (2); desmoplastic small round cell tumor (2); Huntington disease (2); liposarcoma (2); neurogenic muscular atrophy (2); thyroid neoplasm (2); amyotrophic lateral sclerosis (1); angiomyxoma (1); Arrhythmia (1); B-cell neoplasm (1); carcinoma in situ (1); cervical polyp (1); chondrosarcoma (1); chordoma (1); CNS germ cell tumors (1); CNS tumors (1); Cognitive impairment (1); congenital myasthenic syndrome (1); DICER1 syndrome (1); dystrophinopathies (1); extrarenal rhabdoid tumor (1); extraskeletal myxoid chondrosarcoma (1); fibromatosis (1); gastrointestinal tumors (1); granular cell tumor (1); hemangioblastoma (1).
A further 35 diseases each share a sentence with MYOG in 1 paper.